AR (androgen receptor)
Diseases named in the same sentence as AR in open-access papers (continued):
Sharing a sentence is not in itself a finding about the gene and the disease.
cancer (continued). "Such unbiased analyses revealed that AR activity is negatively correlated with genes involved in positive immune processes, suggesting immunosuppressive effects of AR in multiple cancer subtypes." (PMID 41486951, 2026). "We performed a genome-wide gene expression correlation experiment and calculated the Pearson correlation coefficients to assess the relationship between AR activity and the expression of each gene in each cancer type." (PMID 41486951, 2026). "Human kallikrein–related peptidase (KLK) 2, a serine protease, is a downstream target gene of the androgen receptor (AR) involved in cancer progression, but also known to have an AR‐independent function." (PMID 41531507, 2026). "Next, we examined the differences in AR, ER, and PR activity between sexes for cancer types with at least 12 samples from both females and males." (PMID 41486951, 2026). "The role of androgen receptor (AR) signaling in modulating antitumor immune responses has received increasing attention in recent years; however, its broader impact across diverse cancer types and between sexes remains largely unexplored." (PMID 41486951, 2026). "Future studies with larger sample sizes and broader cancer type representation, including subtypes, would help to further clarify the potential role of AR activity in predicting ICB response." (PMID 41486951, 2026). "Our results indicated that AR signaling negatively correlates with the response of patients with cancer to ICB." (PMID 41486951, 2026). "To gain insights into the clinical relevance of AR activity at the pan-cancer level, we evaluated the correlation between AR activity and PFI and OS in TCGA cohorts." (PMID 41486951, 2026). "In this study, we conducted a pan-cancer analysis of sex hormone nuclear receptors, including the AR, estrogen receptors (ER), and progesterone receptor (PR), with extended analysis of AR given our previous findings." (PMID 41486951, 2026). "AR target genes can influence a number of cancer-relevant cellular processes, such as cell cycle, cell death, metabolism, chromatin remodeling, invasion and DNA repair, playing a critical role in cancer metabolism, proliferation, survival and invasion." (PMID 40805269, 2025). "Increased AR gene copy number allows cancer cells to sustain active AR signaling even under reduced androgen levels." (PMID 41079787, 2025). "We have identified a weak partial agonist activity of DOH for androgen receptor (AR) and estrogen receptor alpha (ERα) in responsive cancer cell culture models, whereas D and DA acted as novel AR and ERα antagonists/degraders and apoptosis inducers." (PMID 39779619, 2025). "AR antagonists suppress cancer growth and induce cellular senescence that leads to cell cycle arrest in both androgen-dependent and castration resistant cell lines suggested as the major underlying mechanism to inhibit proliferation." (PMID 40072554, 2025). "Further studies are necessary to fully understand the implications of androgen-receptor expression and to develop more effective targeted therapies for these cancers." (PMID 40286049, 2025). "Most mutations cause a substitution of one amino acid, thus allowing antiandrogens to act as AR agonists and favor cancer progression." (PMID 41153666, 2025). "LNCaP is metastatic AR positive, while 1532NPTX and 1523CPTX are paired primary normal and cancer cells, respectively, isolated from the same patient." (PMID 41509368, 2025). "Androgen receptor (AR) signaling is another critical regulator of cancer‐related autophagy, especially in PCa." (PMID 40900810, 2025). "Similar results were also reported in non-reproductive cancers, with less clarity, and the goal of this review is to gain a comprehensive understanding of current discoveries of testosterone/AR in a few selected cancer types." (PMID 41228208, 2025).
cancer (continued). "By influencing androgen receptor overexpression, cell adhesion, resistance to apoptosis, and epithelial‐mesenchymal transition, miRNAs play important roles in cancer growth and development." (PMID 40839490, 2025). "Similar to other cancers, PCa cells need iron for their survival and growth, including the use of iron for the activity of enzymes that control the expression of androgen receptor, a well-known promotor of PCa." (PMID 40821323, 2025). "They found that their peptidomimetic, named D2, was able to specifically disrupt the binding of PELP1 to AR with an IC50 of 40 nM, preventing AR translocation, resulting in decreased growth of cancer cells in vitro, in vivo, and ex vivo." (PMID 40023399, 2025). "This plasticity enables cancer cells to evade androgen receptor (AR)-signaling dependence, contributing to the resistance against treatments like enzalutamide and abiraterone." (PMID 40722714, 2025). "FOXO1, involved in the development of various cancers, including hormone-dependent ones, influences androgen synthesis and regulates androgen receptor activity." (PMID 40075208, 2025). "In terms of mechanism, DIM can bind to aryl hydrocarbon receptor (AHR), estrogen receptor and androgen receptor (AR) as agonists or antagonists to inhibit proliferation and induce apoptosis in several cancer cell lines." (PMID 40822462, 2025). "These make sense as they are fundamental differences in biology and development between pediatric and adult cancers, with estrogen and androgen receptor signaling playing key roles driving cancer-relevant processes such as proliferation in adult tissues." (PMID 40909678, 2025). "This suggests that the expression of AR is correlated with the degree of differentiation of cancer tissues, with higher expression levels corresponding to higher levels of differentiation." (PMID 40729027, 2025). "As research advances, it has become evident that the regulation of the AR signaling pathway in CRPC is influenced by various elements, including LncRNAs that have recently been implicated in malignant tumors." (PMID 40771930, 2025). "Specifically, HER2 has been shown to increase ligand-independent activation of AR, transactivation of AR, and cancer cell growth at metastatic sites." (PMID 40857406, 2025). "Oncogenic transcription factors (TFs), such as the androgen receptor (AR), cooperate with epigenetic coregulators at cancer-specific enhancer complexes, or neo-enhanceosomes, to drive oncogene expression by promoter looping." (PMID 41044247, 2025). "One of the most frequently observed mechanisms is AR gene amplification and overexpression, resulting in increased levels of AR protein within cancer cells." (PMID 41235005, 2025). "AR expression is enhanced in some cancer types and decreased in other types compared to their corresponding normal tissues, suggesting a complex role of AR, as well as tissue-specific functions of AR in cancers." (PMID 41228208, 2025). "It refers to the ability of cancer cells to adapt and change their cellular identity in response to therapeutic pressures such as AR signaling inhibitors." (PMID 40356745, 2025). "Still, to fully recapitulate the impact of the microenvironment, the effect of RH02211 should be tested in xenograft models using selected AR-negative and AR-positive cancer cells." (PMID 40489535, 2025). "One of the intriguing aspects of CD8+ T cell function in cancer derives from the fact that AR is expressed not only in prostate tissues but also in specific subsets of CD8+ T cells." (PMID 40361239, 2025). "Based on the information above, we propose that HIC1 potentially controls the proliferation and invasion of cancer cells by regulating AR expression and subsequently modulating the IRS2/PI3K/AKT pathway." (PMID 41050263, 2025).
cancer (continued). "By integrating targeted delivery through the AR peptide, this approach not only enhances the accumulation of drugs within cancer cells but also maximizes the therapeutic impact by combining multiple treatment modalities." (PMID 40497249, 2025). "Interactions with HOXB13 and AR-V7, a constitutively active variant of AR that emerges in CRPC, up-regulate genes associated with cancer progression and metastasis." (PMID 40833121, 2025). "Inflammatory messengers, such as IL-6, can also help cancer cells resist therapy by activating survival pathways outside of the AR signaling pathway." (PMID 41235005, 2025). "Despite mounting evidence of AR’s involvement in these cancers, the precise contribution of T/AR in sex disparities, cancer biology, prognosis, treatment responses, and survival is largely unclear." (PMID 41228208, 2025). "PPARG ligands can either suppress or enhance AR signaling depending on the cancer’s response to castration, whereas AR activation reduces PPARG levels." (PMID 40458476, 2025). "Shiota and colleagues showed that comprehensive inhibition of AR signaling, both for normal and aberrant signaling, increases the sensitivity of cancer cells to taxanes." (PMID 39651632, 2025). "Changes in AR co-regulator expression also provide a survival advantage to cancer cells during ADT, promoting progression to CRPC." (PMID 39757310, 2025). "Collectively, Lor and Cir are interesting drug candidates for the treatment of ARV7‐positive cancer, albeit the specificity is not limited to the AR pathway." (PMID 39258426, 2025). "Further investigation is warranted to elucidate the specific factors that dictate when AR signaling promotes or impedes tumorigenesis across distinct cancer types." (PMID 39744510, 2025). "Among the molecularly defined groups now considered clinically actionable are HER2-low tumors and AR-positive cancers." (PMID 41373752, 2025). "Their research revealed that exosomes from AR-silenced cancer cells or those exposed to the androgen receptor antagonist enzalutamide elevated the levels of circular RNA-deoxyhypusine synthase (circ-DHPS)." (PMID 40556678, 2025). "Promote cell proliferation through AR dependent pathway; Affect lipid metabolism, promote the proliferation of cancer cells and fat synthesis." (PMID 41421797, 2025). "Both cancers rely on estrogen receptor (ER) and androgen receptor (AR) signaling, for their initiation and progression, emphasizing the need for advanced therapeutic strategies in disease treatment." (PMID 41295214, 2025). "In the second case (GU-2), an AR-driven CTC subset coexists with a second cancer cell population exhibiting neuroendocrine differentiation." (PMID 39746954, 2025). "Genomic AR signaling involves the direct binding of AR to AREs in the DNA, regulating the transcription of target genes that influence cancer progression." (PMID 40075640, 2025). "Here, we present novel niclosamide pro-drugs for use in advanced HCC based upon niclosamide’s known anti-AR activity and additional anti-cancer pathway efficacy." (PMID 40805231, 2025). "ARD-69 showed superior efficacy compared to existing AR inhibitors, including activity against resistant cancer cells." (PMID 40574056, 2025). "The interactions of ELK1 with MZF1, AR, and ER are some of the most reported in several cancer types, all credited with growth-related phenomena." (PMID 40862737, 2025). "As the rate of recurrence (resistance to conventional chemotherapy) is very high, regardless of the Fisher’s exact test results in this study, nearly all patients with the cancer recurrence exhibited strong AR expression, except for those with CCCA." (PMID 40392873, 2025). "The formation of a ternary complex between the AR and EP inhibits EP function selectively in cancer cells, leading to cell death." (PMID 41374958, 2025). "When PTEN is lost, the PI3K/Akt/mTOR pathway becomes overactive, helping cancer cells survive and making them resistant to standard treatments, such as drugs that block the AR." (PMID 41235005, 2025).
cancer (continued). "The interaction between AR and SEs is of great significance for maintaining the proliferation and metastatic potential of cancer cells." (PMID 40470696, 2025). "Compared to healthy women, PCOS patients exhibit increased androgen receptor expression in the endometrium, facilitating cancer cell implantation and metastasis." (PMID 40534880, 2025). "During PCa, mTOR also directly associates with chromatin in different complexes with transcriptional regulators, including AR, to drive chromatin remodeling and the transcription of genes relevant for cancer progression." (PMID 41009328, 2025). "Among these, LNCaP represents a hormone-sensitive cell line, whereas the other cancer cell lines exhibit resistance to androgen synthesis inhibitor abiraterone and androgen receptor (AR)-inhibitors such as enzalutamide." (PMID 40759693, 2025). "Given that STS is critical to androgen production and plays a role in the AR signaling pathway, it is likely that STS overexpression results in enhanced AR transcriptional activity, mediating metabolic reprogramming in cancer cells." (PMID 40563609, 2025). "TAMs secrete various pro-inflammatory cytokines and growth factors, such as IL-6 and IGFs, which can activate the AR signaling pathway, promoting cancer cell growth and enhancing resistance to therapies, including antiandrogen treatment." (PMID 40008000, 2025). "Inhibiting CBP/p300, particularly through targeting their bromodomains, disrupts AR-driven gene expression and impairs DNA damage repair mechanisms, resulting in reduced cancer cell proliferation and sensitization to standard therapies." (PMID 41235005, 2025). "The primary goal of this design was to effectively degrade the androgen receptor (AR) in cancer cells." (PMID 41220927, 2025). "As AR has previously been reported to have dual roles in HCC, our findings corroborate reports that AR can both contribute to cancer aggressiveness and suppress several oncogenic pathways." (PMID 40805231, 2025). "Earlier studies had reported AR positivity rates of 15–70% for low-grade pTa, 22–70% for high-grade pTaG2/3, and 15–52% for pT2–pT4 carcinomas." (PMID 41463239, 2025). "Our AR positivity rate of 49.8% in low-grade pTaG2, 31.6% high-grade pTa, and 15.5% in pT2–pT4 carcinomas is in the lower range of these studies." (PMID 41463239, 2025). "In pTa carcinomas, AR positivity decreased significantly from 49.8% in low-grade pTaG2 to 29.1% in high-grade pTaG2 tumors (p < 0.0001), with similar levels observed in pTaG3 (31.6%)." (PMID 41463239, 2025). "In vivo studies using an athymic nude mouse model confirmed α-mangostin’s capability to degrade both AR and AR-V7, demonstrating substantial efficacy in reducing cancer growth, especially in CRPC-like conditions." (PMID 39199550, 2024). "In CRPC, cancer cells develop mechanisms to bypass the need for ligand binding to the androgen receptor (AR), rendering them unresponsive to traditional hormone therapies." (PMID 39199550, 2024). "One such pathway involves the GR, which can take over the role of AR in promoting cancer cell growth." (PMID 39184676, 2024). "It was also shown that castration prevented cancer in half of the mice, while completely knocking-out the androgen receptor prevented cancer in all mice." (PMID 39083104, 2024). "Increased activation of the PAM pathway occurs frequently in PC and is associated with cancer progression and acquisition of castration‐resistance and androgen/AR‐independence after ADT or treatment with AR pathway inhibitors." (PMID 39092562, 2024). "On top of that, activation of the AR upregulates antiapoptotic factors, further contributing to cancer cell survival." (PMID 38238434, 2024). "Several coactivators also activate AR-unrelated signaling pathways, such as those of insulin-like growth factors, which inhibit apoptosis in cancer cells." (PMID 38104650, 2024).
cancer (continued). "Together, these findings support that combining androgen receptor blockade with ICIs is a promising future cancer research direction." (PMID 38539486, 2024). "This suggests that AR can be used as a therapeutic target in the treatment of BC and as an alternative to traditional cancer therapies like chemotherapy." (PMID 39399414, 2024). "AR is a key mediator of androgen signaling, playing significant roles in both normal physiology and cancer." (PMID 39769441, 2024). "This suggests an elevated level of local CD8+ T cell exclusion in these cancers, which appears to be mediated by AR signaling." (PMID 39591176, 2024). "To determine the impact of AR or AR-V7 in a prostate cancer model, we utilized our lentiviral vectors to express these genes in a murine cancer cell line, which was derived from a murine prostatic carcinoma." (PMID 39591176, 2024). "More than 2650 articles listed in PubMed® have described immunohistochemical evaluations of AR in cancer (PubMed® search (10/23: “androgen receptor cancer immunohisto*”)." (PMID 38790919, 2024). "Additional studies are needed to evaluate if this AR-regulated signaling is conserved in driving other cancer types." (PMID 38326303, 2024). "The androgen receptor-based polyproline peptide on both cancer cells playing the role of inhibitor is one of the appealing therapies." (PMID 39409876, 2024). "In situ expression analyses in normal and cancer tissues demonstrated a statistically significant correlation between androgen receptor (AR) expression and genes involved in lysosomal vesicular trafficking." (PMID 39217195, 2024). "AR is a key driver of PCa pathophysiology, regulates cancer cell proliferation, metabolism, and migration, is an empirical therapeutic target for PCa and is crucial for the development of resistance to ADT." (PMID 37847340, 2024). "Patients treated with enzalutamide showed increased levels and transcriptional activity of GR, leading to partial but significant reactivation of AR target gene expression and cancer progression." (PMID 39027480, 2024). "In contrast, dysregulated HOXB13 expression promotes androgen receptor-independent function and cancer cell proliferation." (PMID 38201640, 2024). "This transition is often driven by the activation of lineage plasticity and reprogramming pathways, allowing the cancer to adopt a more aggressive phenotype that is resistant to standard AR-targeted therapies." (PMID 39184676, 2024). "Shorter CAG repeats in African American men contribute to higher AR signaling and potentially more aggressive cancer." (PMID 39600743, 2024). "Their targets are related to different cancer hallmarks and to the expression of biomarkers commonly used in PCa diagnosis like AR or PSA." (PMID 38542079, 2024). "Some cancers adapt to low-androgen environments by altering AR signaling, which supports their survival and proliferation." (PMID 39296545, 2024). "Consistent with this upstream regulator analysis, CA3 exposure in CCA cells was associated with increased AR protein levels, and combinatorial therapy with CA3 and androgen receptor blockade was associated with increased cancer cell death." (PMID 39300603, 2024). "The AR has been meticulously studied in cancers that display hormone sensitivity, like the prostate and breast cancers mentioned." (PMID 38362126, 2024). "Despite the initial effectiveness of the antiandrogen therapies, the cancer often develops resistance to the AR blockade." (PMID 38015476, 2024). "Caucasian men generally exhibit longer CAG repeats in the AR gene, leading to lower AR transactivation potential and a less aggressive cancer phenotype." (PMID 39600743, 2024). "AR not only impacts cellular processes like energy metabolism and apoptosis but also mitochondrial function, playing a crucial role in the cancer’s behavior and treatment outcomes." (PMID 39296545, 2024).